MCL1 (MCL1 apoptosis regulator, BCL2 family member)
Diseases named in the same sentence as MCL1 in open-access papers (continued):
Sharing a sentence is not in itself a finding about the gene and the disease.
infection (continued). "However, recognized virulence determinants known to be expressed at distinct infection steps, such as the destruxin backbone gene and the collagen-like protein gene Mcl1, were found methylated, suggesting that a dynamic pattern of methylation could be found during the infectious process." (PMID 31711419, 2019). "A similar model applies to the infection of CD14+ cells, whereby MCL-1 upregulation was also demonstrated to be required for the survival of CD14+ monocytes following HCMV infection." (PMID 29547547, 2018). "In the present study, after infection with AdC7-SP/E1A-ΔE3, NCI-H508 cells had declining levels of antiapoptotic protein MCL-1 and Bcl-2, whereas Huh7 cells had decreased expression of MCL-1and Bcl-xl." (PMID 28460470, 2017). "However, it is so far unknown by which mechanism C. trachomatis stabilize Mcl-1 upon infection." (PMID 28347402, 2017). "Infection with GLV-1h68 was also shown to downregulate a number of anti-apoptotic proteins, such as MCL-1, BCL-XL and the IAP family." (PMID 27783991, 2016). "Similar data were obtained using MS74 cells, infection with T. vaginalis resulted in a MOI-dependent cleavage of Bcl-xL and Mcl-1." (PMID 25343522, 2014). "Mcl-1 induction was quantitatively defined by real-time RT-PCR at 16 hours post-infection, showing that both U0126 and LY294002 significantly reduced the Mcl-1 induction in both cell lines, compared to the control cells treated with DMSO alone." (PMID 22253918, 2012). "Bak and Mcl-1 knockdown and control H1299 cells infected with IBV at an M.O.I. of 1, harvested at various time points from 0 to 20 hours post-infection, and total RNA was extracted for Northern blot analysis, followed by densitometry measurements." (PMID 22253918, 2012). "Infection with C. trachomatis leads to the MEK-dependent up-regulation of Mcl-1 mRNA and PI3K-dependent stabilization of Mcl-1 protein levels." (PMID 18769617, 2008). "Infection leads to the Raf/MEK/ERK-mediated up-regulation and PI3K-dependent stabilization of the anti-apoptotic Bcl-2 family member Mcl-1." (PMID 18769617, 2008). "GSK-872 reduced Mcl-1 protein levels specifically in C.t.-infected, but not in uninfected neutrophils, indicating that the elevation of Mcl-1 levels upon infection depends on RIP3 activity and the induction of necroptosis." (PMID 41051248, 2025). "The inhibition of Mcl-1 by Umi-77 did not affect Mcl-1 levels, which were still increased upon infection of neutrophils." (PMID 41051248, 2025). "For other anti-apoptotic gene expressions, we found that MCL1 was upregulated, except in homeostatic Micro-0 and Micro-1, CFLIP (CFLAR) was upregulated in Micro-3 and Micro-11, and others remained unchanged or slightly downregulated in infection." (PMID 39283947, 2024). "WB analysis of RVFV infected cell lysates showed that MCL-1 was rapidly down-regulated in RVFV-infected cells 6 hours post infection while the abundance of BCL-xL was not affected." (PMID 39213434, 2024). "Genes upregulated for the BCL-2 family of antiapoptotic proteins (MCL1 in LMH cells, and BCL2A and BCL2L14 in CEK cells infected with either strain of ILTV), were in agreement with the notion that ILTV infection prevents apoptosis of infected cells, in order to prolong viral replication." (PMID 39392810, 2024). "Reports suggest enhanced RNA and protein levels of MCL-1 during infection by virulent but not attenuated strains of Mycobacterium tuberculosis." (PMID 35531875, 2022). "Mcl-1, Bcl-w and Bcl-XL are, therefore, not essential to the inhibition of apoptosis by Ctr-infection." (PMID 35397654, 2022). "Although it has been suggested that MCL-1 can be found in both acute and chronic models of M. tb infection, the MCL-1 expression increases mainly after 16 weeks of infection, accompanied by a change in the macrophage phenotype towards M2, characterized by an anti-inflammatory profile." (PMID 35631013, 2022).
infection (continued). "In concordance with the transcription level, the MCL-1 protein level was not modified after infection with either an avirulent or a virulent M. tb strain." (PMID 35631013, 2022). "Mcl-1-specific staining intensity essentially doubled among neurons at multiplicity of infection (MOI) 100, versus nontransduced controls, indicating that widespread recombinant expression had occurred." (PMID 31227712, 2019). "The increase in Bcl-2 occurs largely in response to the up-regulation of pro-apoptotic Bax following infection, which can be inactivated by Bcl-2, but not Mcl-1." (PMID 30274264, 2018). "Although the overexpression of dominant negative Cullin-1 (DN-CUL1) led to an upregulation of MCL1 in non-infected cells, infection with JEV still suppressed MCL1 expression." (PMID 30261081, 2018). "Secondly, MCL-1-mediated protection from apoptosis is a relatively transient event in CD34+ cells, with latently infected CD34+ cells no longer protected from cisplatin A-induced apoptosis 12 h post-infection." (PMID 29547547, 2018). "Since Mcl-1 and Cdu1 interact with each other and share the same subcellular localization during infection, Cdu1 expression should stabilize Mcl-1 even in the absence of infection." (PMID 28347402, 2017). "Mcl-1 also has no role in controlling macrophage apoptosis in response to infection with these viruses." (PMID 27537523, 2016). "Macrophages knocked down for either Bcl-2 or Mcl-1 showed no significant impact on viability upto 48 h of infection." (PMID 27826299, 2016). "When we tested for an Mcl-1-replacing activity we found it during neither MVA nor VACV infection of macrophages." (PMID 27537523, 2016). "Mcl-1, in contrast to its essential role in many other situations, has no role in the regulation of survival during infection with MVA/VACV or MCMV." (PMID 27537523, 2016). "Unlike during infection of fibroblasts, MVA was unable to protect Mcl-1-deficient macrophages against ABT-737; a sensitization to ABT-737 was even seen during VACV infection." (PMID 27537523, 2016). "Furthermore, infection of the SiHa cells with T. vaginalis resulted in a MOI-dependent cleavage of Bcl-xL and Mcl-1 in the SiHa cells." (PMID 25343522, 2014). "Bad was also suppressed after infection of THP-1 by M. leprae in a previous study where authors observed that irradiated M. leprae inhibits apoptosis by diminishing pro-apoptotic Bad and Bak mRNA expression, while inducing the anti-apoptotic gene Mcl-1." (PMID 23798993, 2013). "An intriguing feature of S. aureus-induced Mcl-1 expression was the synthesis of an alternatively spliced MCL1 gene product (MCL1S proapoptotic isoform), which was observed at the mRNA level early after infection." (PMID 23431241, 2013). "We also used qRT-PCR to validate the pre-clinical over-expression of 4 of these genes previously unrecognized as playing a role in prion pathobiology; RASGRF2, TRIB1, MCL1 and HOMER1 were all confirmed to be up-regulated during the same time period post-infection in CA1 pyramidal neurons." (PMID 23144617, 2012). "The induction of Mcl-1 and Bak was also examined quantitatively by real-time RT-PCR, which, after normalization to UV-inactivated IBV-infected cells, showed significant induction in Vero, H1299 and Huh7 cells infected with live IBV at 16 hours post-infection." (PMID 22253918, 2012). "Interestingly, at 24 h after infection we observed enhanced systemic expression of antiapoptotic genes (e.g. CFLAR, MCL1)." (PMID 20184744, 2010). "Similarly, Myeloid Cell Leukemia 1 (MCL1) showed a progressive increase from severe alive to severe dead patients, indicating its involvement in cell survival and apoptosis regulation during severe infection." (PMID 39928675, 2025). "Even a 2-hour Umi-77 exposure did not compromise neutrophil viability, indicating that infection could not extend neutrophil lifespan under sustained Mcl-1 inhibition." (PMID 41051248, 2025).
infection (continued). "However, the strength of protection by Ctr-infection (measured as fold-reduction of cells undergoing apoptosis) was similar in the presence and absence of Mcl-1." (PMID 35397654, 2022). "Therefore, increased abundance of two Bcl-2 family members (MCL1 and BCL2A1) at an early time post-infection in THP-1 macrophages by R. conorii may be a strategy to promote host cell survival and retain a replicative niche." (PMID 31024862, 2019). "However, unlike in CD34+ cells, MCL-1 levels remain elevated in CD14+ monocytes until at least 48 h post infection (hpi), a long time after the initial binding events responsible for triggering its upregulation." (PMID 29547547, 2018). "Nevertheless, Mcl-1 did have a role in protecting macrophages against ABT-737 (compare apoptosis induced by ABT-737 in wt and Mcl-1-deficient cells), yet there was no protection by MVA infection in Mcl-1-deficient cells." (PMID 27537523, 2016). "Mcl-1 protein (but not mRNA) is reduced or lost upon infection with MVA/VACV." (PMID 27537523, 2016). "In support, siRNA-mediated knock down of Mcl-1 levels leads to a reversal of the apoptotic resistance observed in HCMV-infected monocytes, confirming that Mcl-1 is responsible for the enhanced survival of monocytes during the initial 24–48 hours following infection." (PMID 24531335, 2014). "Furthermore, Bak and Mcl-1 may play key roles in the regulation of IBV-induced apoptosis, not only at an early stage of infection in vitro, but also at a late stage of infection in vivo." (PMID 24168272, 2013). "Taken together, these results confirm that Mcl-1 may play a part in the regulation of IBV-induced apoptosis, and a decrease in the Mcl-1 expression in cells could enhance IBV-induced apoptosis at earlier stages of infection." (PMID 22253918, 2012). "As no significant amount of Mcl-1 was observed in siEGFP-transfected H1299 and Huh7 cells at 24 hours post-infection, it may suggest rapid proteasome degradation of the protein as observed previously." (PMID 22253918, 2012). "Furthermore, we identify in the current study that Bcl-2, mcl-1, and hsp-70 and-27 are not affected during the entire time course of the infection, supporting the essential role of Bim in the mitochondria, and not other apoptotic proteins, in the context of HIV." (PMID 30850623, 2019). "During infection of epithelial cells and fibroblasts with modified vaccinia virus Ankara (MVA), Mcl-1 protein levels dropped but the MVA Bcl-2-like protein F1L could replace Mcl-1 functionally; a similar activity was found in vaccinia virus (VACV)-infected cells." (PMID 27537523, 2016). "Infection with MCMV did not alter expression of Mcl-1 in HeLa and even induced Mcl-1 expression in MEFs." (PMID 27537523, 2016). "During infection with murine cytomegalovirus (MCMV), Mcl-1-levels were not reduced but a viral Mcl-1-like activity was also generated." (PMID 27537523, 2016). "Mcl-1 is thus not involved in the regulation of survival and apoptosis during MVA infection in macrophages, but Bcl-XL has a role in keeping infected macrophages alive." (PMID 27537523, 2016). "In the absence of F1L, MVA induces apoptosis upon infection of HeLa and MEF cells,22 suggesting that a molecular function of F1L is the replacement of Mcl-1." (PMID 27537523, 2016). "Significantly more apoptotic cells were observed in Mcl-1 knockdown cells infected with IBV compared to the control cells transfected with siEGFP, or with Bak-knockdown cells at both 20 and 24 hours post-infection, whereas little or no apoptotic cells were observed in mock-infected cells." (PMID 22253918, 2012). "HeLa cells induced at the late phase of infection, when the cells contained mainly large inclusions, failed to respond to GrB upon inhibition of MAPK, suggesting that apoptosis resistance during the late stage of infection is independent of MAPK and Mcl-1." (PMID 18769617, 2008).
infection (continued). "Moreover, screening the network interactions among the genes involved in cell death/survival for both the LV and Lena strains showed that the canonical apoptosis pathway signals (BID, CASP8, MCL1 and NFKB) were activated upon LV infection, but not following Lena infection." (PMID 24643046, 2014).
hematological malignancies (83 papers, 2014 to 2026). "Activation of these pathways has been linked to reduced sensitivity to MCL1 inhibition in both solid tumors and hematologic malignancies." (PMID 41155156, 2025). "As an antiapoptotic protein, MCL-1 has become an attractive target and is implicated with venetoclax resistance in hematologic malignancies, motivating us to investigate AZD5991 alone and in combination with venetoclax in our resistant MCL models." (PMID 37919300, 2023). "MCL-1 plays a vital role in the development of hematological malignancies and high expression of MCL-1 is associated with BCL-2 inhibitor resistance." (PMID 35794605, 2022). "S-63845 is a selective BH3 mimetic Mcl-1 inhibitor that causes apoptosis of various Mcl-1 dependent hematologic malignancies by activating the Bax/Bak dependent mitochondrial apoptotic pathway." (PMID 35884390, 2022). "The aim of this study was to identify subsets of patients with hematological malignancies susceptible to the combined treatment with the MCL1 antagonist S63845 in combination with the MDM2-inhibitor HDM201 or the MEK-inhibitor trametinib." (PMID 31718075, 2019). "Given that voruciclib has completed two Phase 1 clinical trials, it may represent the most clinically advanced orally available therapy to inhibit MCL-1 for use in combination with venetoclax to treat high-risk hematological malignancies." (PMID 29269870, 2017). "BCL2L1 upregulation is a resistance factor of MCL1 inhibitor response in solid tumors and hematological malignancies." (PMID 39846250, 2025). "First, marinopyrrole A and its derivatives validate Mcl-1 as an actionable vulnerability, particularly in hematological malignancies and solid tumors resistant to other BH3-mimetics." (PMID 41149606, 2025). "BH3 mimetics, a novel class of small molecule inhibitors that bind and inhibit anti-apoptotic members of the BCL2 family proteins such as BCL2 or MCL1, have been very successful in treating hematologic malignancies." (PMID 38459020, 2024). "Overexpression of BCLX, BCLW, MCL1, and/or BFL1 causes resistance to venetoclax and navitoclax in hematologic malignancies." (PMID 38893249, 2024). "This inhibitor designed to bind to the BH3-binding groove of MCL-1 has shown a high efficacy (IC50 < 1 μM) in vivo in mouse models of hematological malignancies." (PMID 37835493, 2023). "Currently, known mechanisms, such as MCL-1 dysregulation triggered by CDK9 in hematological malignancies and solid tumors, have mainly been discovered using pan-CDK inhibitors." (PMID 37272701, 2023). "In preliminary studies in T-PLL, CDK9 inhibition decreased the expression of JAK/STAT related transcripts, c-Myc, and Mcl-1 [as has been observed in other hematologic malignancies]." (PMID 37569479, 2023). "Several Mcl-1 inhibitors are currently being investigated in clinical trials for various hematological malignancies." (PMID 37371761, 2023). "Myeloid cell leukemia-1 (MCL-1) was highly expressed in multiple hematological malignancies, and was shown to mediate the development of hematological malignancies, including AML." (PMID 35794605, 2022). "In leukemic cell survival, miRNAs-15/16 is inversely correlated with the levels of oncogenes, such as B-cell lymphoma 2 (Bcl2), which is expressed in several haematological diseases, myeloid cell leukemia-1 (MCL1), JUN, and WNT3a." (PMID 35055013, 2022). "The Mcl-1 gene is located on chromosome 1q21, a region that is frequently subjected to alterations in a myriad of solid tumors and hematological malignancies." (PMID 36045907, 2022). "AMG-176 is a selective Mcl-1 inhibitor that disrupts the interactions of the Mcl-1-Bak complex and has been reported to induce rapid apoptosis in different hematologic malignancies." (PMID 35884390, 2022).
hematological malignancies (continued). "Clinical evaluation of MCL-1 inhibitors for hematological malignancies is currently underway, with a major clinical objective to determine a safe therapeutic window for this class of inhibitors, in accordance with physiological roles of Mcl-1." (PMID 35163413, 2022). "AZD-5991 is a BH3-antagonist, highly selective for MCL1 and under investigation in Phase I/II clinical trials for hematologic malignancies (ClinicalTrials.gov Identifier NCT03218683)." (PMID 33803266, 2021). "MCL-1 also has high oncogenic potential and is upregulated in a range of malignancies, including solid tumors and hematological malignancies." (PMID 33883020, 2021). "AMG-176 is a first-in-class Mcl-1 inhibitor in clinical development for hematologic malignancies that has shown activity in inducing CLL cell death and has shown an additive or synergistic effect in combination with venetoclax." (PMID 35070982, 2021). "High levels of MCL-1 have been reported in hematological malignancies and a wide range of solid tumors." (PMID 33883020, 2021). "High levels of Mcl-1 have been also reported in hematological malignancies and subsequently in a wide range of solid tumors, including breast, ovarian, prostate, pancreatic and non-small cell lung (NSCLC) carcinoma." (PMID 32455818, 2020). "Preclinical studies with “modern” MCL-1 inhibitors strongly pointed to hematological malignancies as prime indications for early clinical testing." (PMID 33308268, 2020). "Overexpression of mitochondrial protein MCL1, a common feature in hematologic malignancies, was associated with venetoclax-resistance in AML VU661013, a selective MCL1 inhibitor able to induce apoptosis in AML cells, overcoming venetoclax resistance." (PMID 32486249, 2020). "While solid tumors only displayed dependencies toward MCL-1, hematological malignancies were dependent on both MCL-1 and BCL-2." (PMID 33308268, 2020). "The success story of BCL-2 inhibitors in hematologic malignancies is quite encouraging, along with new MCL1 and IAP inhibitors that are actively being tested in the clinic." (PMID 31370269, 2019). "Mcl-1 plays a pivotal role in evading cell death in response to various apoptotic stimuli in solid tumors and hematologic malignancies." (PMID 26219338, 2015). "Meanwhile novel compounds targeting MCL-1 in hematologic malignancies are entering clinical trials." (PMID 39912943, 2025). "Interestingly, the mechanism of action of some MCL1 inhibitors used in hematological malignancies is the induction and increase in Mcl1 protein stability." (PMID 38256213, 2024). "However, resistance against ABT-737 has been reported in several preclinical models of different hematological diseases, mainly due to the expression of Mcl1." (PMID 39684550, 2024). "MCL1-selective inhibitors may represent a new class of anticancer agents that could provide clinical benefit to patients with a variety of hematological malignancies and solid tumors." (PMID 37900961, 2023). "In addition, Mcl-1 inhibitors are currently being investigated in clinical trials for various hematologic malignancies." (PMID 37371761, 2023). "In addition, several Mcl-1 inhibitors have entered clinical evaluation in patients with hematological malignancies, of which S64315 (MIK665) is chemically related to S63845 (used here), and has shown comparable activity." (PMID 36902392, 2023). "Among the antiapoptotic Bcl-2 family members, predominant overexpression of the prosurvival myeloid cell leukemia-1 (Mcl-1) has been reported in a myriad of hematological malignancies and solid tumors, contributing to therapy resistance and poor outcomes, thus making it a potential druggable target." (PMID 36045907, 2022).